RN7SL405P (RNA, 7SL, cytoplasmic 405, pseudogene)
Gene: Miscellaneous RNA gene on chromosome 17 (44,883,986 to 44,884,274, forward strand). Ensembl gene ENSG00000264540.
Homologues: Orthologues: chimpanzee Metazoa_SRP (99% identical), macaque Metazoa_SRP (76% identical). Paralogues in human: Metazoa_SRP (74% identical), Metazoa_SRP (73% identical), RN7SL670P (72% identical), Metazoa_SRP (68% identical), Metazoa_SRP (59% identical), Metazoa_SRP (58% identical), Metazoa_SRP (57% identical), Metazoa_SRP (54% identical), Metazoa_SRP (51% identical), Metazoa_SRP (48% identical), Metazoa_SRP (47% identical), Metazoa_SRP (46% identical), and 696 more.